GHDC (GH3 domain containing)
Synonyms: LGP1; D11LGP1
Tractability: Antibody: its Gene Ontology location is reachable by antibodies, with high confidence; UniProt predicts a signal peptide or a membrane-spanning region. PROTAC: its protein half-life has been measured.
Gene: Protein-coding gene on chromosome 17 (42,188,799 to 42,194,513, reverse strand). Ensembl gene ENSG00000167925.
Subcellular location: Endoplasmic reticulum; Nucleus envelope
Pathways (Reactome):
Immune System: Neutrophil degranulation
Gene Ontology:
Cellular component: membrane; endoplasmic reticulum; extracellular region; nuclear envelope; secretory granule lumen; specific granule lumen
Genetic constraint (gnomAD): Loss-of-function variants: 44 observed, 50.19 expected, observed/expected ratio (o/e) 0.88, 90% interval 0.69 to 1.13. The upper end of that interval is the gene's LOEUF score, 1.13, which puts it in group 4 of 6, group 1 being the genes least tolerant of losing a copy. Missense variants: 610 observed, 608.82 expected, observed/expected ratio (o/e) 1, 90% interval 0.94 to 1.07. Synonymous variants: 282 observed, 271.54 expected, observed/expected ratio (o/e) 1.04, 90% interval 0.94 to 1.15.
Homologues: Orthologues: chimpanzee GHDC (98% identical), macaque GHDC (95% identical), pig GHDC (84% identical), dog GHDC (83% identical), rat Ghdc (74% identical), mouse Ghdc (74% identical), rabbit GHDC (70% identical), tropical clawed frog ghdc (37% identical), zebrafish ghdc (36% identical).
Diseases named in the same sentence as GHDC in open-access papers:
GHDC is named in the same sentence as 7 diseases in open-access papers, as found by Europe PMC text mining. Sharing a sentence is not in itself a finding about the gene and the disease.
GHDC shares sentences with these, for which no sentence is quoted: Diabetes (1 paper); diabetic nephropathy (1); glioblastoma multiforme (1); glioma (1); Hyperglycaemia (1); Hypoglycemia (1); tumor (1).